BCL2 (BCL2 apoptosis regulator)
Diseases named in the same sentence as BCL2 in open-access papers (continued):
Sharing a sentence is not in itself a finding about the gene and the disease.
tumor (continued). "However, the majority of the antigens described thus far are dispensable for the survival and growth of the tumor cells, with the exception of a few TAAs such as telomerase, survivin and anti-apoptotic members of the Bcl-2 family (Bcl-2, Bcl-X(L) and Mcl-2)." (PMID 23437226, 2013). "Overexpression of antiapoptotic Bcl2 proteins is observed in many tumor types, which may contribute to the drug-resistant state and help mediate the expansion of a transformed population by disrupting normal cell turnover." (PMID 23956872, 2013). "Moreover, antisense oligonucleotides targeting Bcl-2 and Bcl-XL sensitized tumor cells to the cytostatic effect of cisplatin." (PMID 23817665, 2013). "In addition, factors, such as HMGA1, Bcl-2, SirT1, N-Ras, K-RAS, Ezrin, Mucin 4, E2F and metastasis-associated gene (MTA1), are also involved in tumor invasion and metastasis." (PMID 23325049, 2013). "Bcl-2 is expressed at a high concentration in many tumor cells and is involved in drug resistance." (PMID 23599800, 2013). "Protein analysis of tumor tissue lysates from three mice in each treatment group indicated that niclosamide blocks erlotinib-stimulated STAT3 phosphorylation leading to decreased Bcl2 and Bcl-XL levels." (PMID 24019973, 2013). "This evidence indicates that the rutin has regulatory role in the BCL2/BAX balance of tumor cells." (PMID 24459422, 2013). "Moreover, combination of ADT and chemotherapy also resulted in an increased epithelial Bcl2 and nuclear pAKT expression, emphasizing the role of Hh signaling activation in tumor progression." (PMID 23880852, 2013). "In addition, crocin (6.25, 25 mg/kg) inhibited the tumor weight and size of HL-60 xenografts in nude mice, inhibited Bcl-2 expression, and increased Bax expression in xenografts." (PMID 23573146, 2013). "Also, to dissect out the benefit of anti-oxidant rich seaweed polyphenols in targeting tumor progression markers, first, we investigated the transcriptional regulation of Bcl2, EGFR, PDGFA, VEGF, AKT, TERT, kRas and FGF in PC cells." (PMID 23613993, 2013). "The oncogenes MET, MYC, BCL2 (yellow and blue subgroups) were down-regulated in normal vs tumor." (PMID 23405235, 2013). "In addition, melatonin prevents free radical damage in normal and tumor tissues, and induces the apoptotic mitochondrial pathway by reducing Bcl2 expression and caspase-3 activity." (PMID 24367487, 2013). "Interestingly, expression of CD10 and Bcl-2 were expressed at the outermost epithelial cell layer of the tumor lobules in a few areas." (PMID 24354761, 2013). "Using ILBC cell lines, primary tumors and pre-invasive lesions as a model, the present work aimed to determine whether reciprocal upregulation of BCL2 is an important determinant of tumor development driven by inactivation of CDH1/E-cadherin." (PMID 24023670, 2013). "Since both TCF and BCL2 were observed to be under the guidance of BMI1, we next investigated whether there is a direct association of TCF and BCL2 gene in tumor cells." (PMID 23671559, 2013). "Besides, BCL2 protein is expressed by a variable proportion of the tumor cells in 85-90% of cases of low-grade FL, but only 50% of high-grade FL using standard antibodies." (PMID 24047469, 2013). "E-cadherin-negative IDBC is a very uncommon tumor phenotype and, possibly due to the extremely small sample size, also lacked a significant association with the BCL2 status." (PMID 24023670, 2013). "As ILBC is the key tumor entity associated with loss of E-cadherin expression, this suggests that reciprocal regulation of BCL2 is not a major mechanism of tumor development driven by CDH1 inactivation." (PMID 24023670, 2013).
tumor (continued). "We observed that DOX4 alone (one or two injections) could impede tumor growth only in a modest and transitory manner and that the tumoral “escape” was accompanied by increases in anti-apoptotic markers like Bcl2 and Surv." (PMID 23705792, 2013). "Similarly, silencing or pharmacological inhibition of Rac1 also compromised Bcl-2-induced increase in intramitochondrial O2∙− levels leading to sensitization of those tumor cells to apoptotic triggers." (PMID 22593827, 2012). "However, BCL2 itself seems to act as both an oncogene and a tumour suppressor gene in different tumour types." (PMID 23961365, 2012). "Modulation of Bcl-2-pathway with simvastatin was also observed in PC3 tumor lysates." (PMID 22974127, 2012). "The sub-cellular localization of Bcl-2 and Bcl-XL was similar in normal and tumour tissue." (PMID 22852863, 2012). "In summary, we have shown that the combination of Bcl-2 inhibitor AT-101 (conditioning of PC cells) with targeted immunotherapy using EGFRBi armed ATC offers an attractive therapeutic approach that can lead to reduced toxicity but potent anti-tumor activity." (PMID 23185240, 2012). "Furthermore, our in vivo data showed that BEAS-Cr cells formed tumors in nude mice and that Bcl-2 knockdown substantially inhibited the tumor formation." (PMID 22666341, 2012). "Nonetheless, our findings suggested clinical application for treatment management in patients bearing gemcitabine resistant tumours that expressed Bcl-2, and may benefit from the synergistic interaction of combination therapy with gossypol." (PMID 23226540, 2012). "Importantly, coexpression of MYC together with BCL-XL/BCL-2 resulted in strongly accelerated kinetics and favored tumor development towards aggressive AML." (PMID 22393362, 2012). "As the transcription of apoptosis related genes could help to elucidate the pathogenesis of tumours, we propose to investigate the quantitative expression of BCL-2 (anti-apoptotic), BAX and Caspase3 (pro-apoptotic genes) using qPCR." (PMID 22313995, 2012). "Knockdown of bcl-2 by shRNA was able to induce apoptosis in many tumor tissues." (PMID 22262940, 2012). "To study the effects of pardaxin on tumor functions, we performed a real-time RT-PCR analysis of caspase-3, caspase-7, caspase-8, caspase-9, Bax, Bcl-2, STAT2, ATF3, STAT3, SOCS3, IL-2, cathelicidin, TNF-α, MyD88, NF-κB1, p65, IFN-β1, IFN-γ, IL-1β, IL-6, IL-7r, and IL-10." (PMID 23015777, 2012). "Also in line for a tumor suppressor role for miR-15b is its direct regulation of the critical anti-apoptotic Bcl-2 protein." (PMID 22857597, 2012). "This anti-tumor activity was also associated with decreased expression of NF-κB target anti-apoptotic, cell proliferative, and tumor promoting genes (Bcl-2 and C-IAP1) but with increased expression of their target apoptotic genes; cleaved caspase-3 and 9, and Bax." (PMID 22567084, 2012). "While combination of targeted therapies with chemotherapeutic drugs has been tested against PC, this is the first study, to the best of our knowledge, to report that priming of tumor cells with highly specific Bcl-2 inhibitor enhances cytotoxic activity armed ATC." (PMID 23185240, 2012). "We, therefore, tested whether cell death can be enhanced in a tumor-specific manner by targeting additional antiapoptotic Bcl-2 proteins." (PMID 22292048, 2012). "Cell death is accelerated by hypoxia and starvation induced by tumor scale, by modification of anti-apoptosis with as-bcl-2, and by direct kill effects of rituximab (cell kill by cytotoxic immune cells is not included, due to the absence of an immune system in the corresponding experiments)." (PMID 23272153, 2012).
tumor (continued). "Since Bcl-2 and Bcl-XL are anti-apoptotic proteins, they are expected to function as oncogenes in cancer cells and pro-apoptotic proteins such as Bax are expected to act as tumour-suppressors." (PMID 22852863, 2012). "Tumours with scores 0–1 were grouped together (low tumour expression of BCL2; n = 35), and the remaining two groups were score 2 (medium tumour expression of BCL2; n = 68) and score 3 (high tumour expression; n = 145)." (PMID 23961365, 2012). "When analyzing the prognostic value of Ki-67 in LMS, the authors concluded that this marker alone could be used as a survival indicator in LMS patients, although combination of tumor size, mitotic index, and Bcl-2 and CD163 expression worked even better." (PMID 22910809, 2012). "The relationship between tumour BCL2 protein expression and oestrogen has also been widely debated." (PMID 23961365, 2012). "Thus ABT-737 is ineffective in killing tumor cells expressing high levels of Mcl-1 compared with those of Bcl-2/Bcl-xL." (PMID 22703841, 2012). "Bcl-2 proteins play a central role in regulating survival of tumor cells." (PMID 22292048, 2012). "Recent reports suggest that in addition to cell proliferation and migration, endothelial cell survival and death are also important components for tumor angiogenesis which is in part mediated by vascular endothelial growth factors by inducing expression of anti apoptotic protein Bcl-2." (PMID 22507529, 2012). "In contrast, the expression of Bcl2 was down-regulated in the SLWLQY-treated tumor tissues (7(c))." (PMID 19383839, 2011). "It was previously demonstrated that Bcl-2 could inhibit apoptosis and also inhibit multiple DNA-repair pathways; thus, tumour cells exposed to DNA-damaging substances, like nitrosamine, exhibited an accumulation of Bcl-2 in the nuclei." (PMID 22214480, 2011). "Our findings provided evidence that TW-37 could act as a small-molecule Bcl-2 inhibitor on well-characterized PC cells in culture as well as when grown as tumor in a xenograft model." (PMID 21760983, 2011). "Taken together, these results suggest that co-treatment of Bcl-2 inhibitor might be important for chemotherapeutic strategy of HBV pre-S2Δ large surface protein containing tumor cells." (PMID 22216150, 2011). "The anti apoptotic protein bcl-2 was strongly co-expressed with ER+ and PR+ tumours." (PMID 24212814, 2011). "This notion could be confirmed by ex vivo analysis of Bcl-2 reactive T cells which were capable of killing HLA-matched tumor cells." (PMID 21304176, 2010). "The expression level of the antiapoptotic protein Bcl-2 in the stromal cultures obtained was heterogeneous: in some tumour stromal cultures (L2T, L3T, L7T, L8T, L10T, L11T and E1T) the Bcl-2 expression was upregulated, whereas in some others (L1T, L4T, L5T, L9T and L13T) downregulated." (PMID 20407446, 2010). "Indeed, tumor tissues from cinnamon extract treated mice showed a significant decrease in the levels of Bcl-2 and BcL-xL compared with control group." (PMID 20653974, 2010). "Further, we demonstrated that the expression of antiapoptotic factors, particularly those of Bcl-2 and survivin, changed significantly in relation to tumor grading, with higher expression levels of BCL-2 in low grade tumors and strongly prominent expression of survivin in high grade tumors." (PMID 24281089, 2010). "In these previous studies, sets of genes associated with pathways such as apoptosis (e.g., bax, bcl-2), DNA damage repair (e.g., Ku80, GADD45, XRCC5), cell adhesion (e.g., ICAM-3), angiogenesis (e.g., HIF-1a), and tumor cell invasion (e.g., CTSL, CTSB) were identified." (PMID 20184742, 2010).
tumor (continued). "Bcl-2 has been found to induce tumor growth and confer resistance to chemotherapeutic agents in xenograft models of human non small cell lung cancer (NSCLC) and Bcl-2 inhibition seems to contribute to reversal of drug resistance in a variety of cancer cell line models." (PMID 20459695, 2010). "Therefore, it is possible that the combination of bcl-2 reduction and Bax elevation, resulting in a greatly decreased bcl-2/Bax ratio, also plays a major role in tumor cell growth inhibition and enhanced apoptosis observed in our model." (PMID 20178622, 2010). "Additionally, Bax expression was increased, whereas Bcl2 expression was decreased in xenograft tumor sections." (PMID 20813046, 2010). "Our data showed that single application of mdr1b/1a siRNA and cyclophosphamide resulted in a decrease in the MDR and a threefold decrease in the tumor size as compared with the control animals treated only with cyclophosphamide, while bcl-2 siRNA was ineffective in vivo." (PMID 20470373, 2010). "Altogether, these results suggested that a very high expression of Bik could be only the reflection of an adaptation of the tumour to high Bcl-2 levels." (PMID 21063407, 2010). "The mdr1b/1a siRNA-induced decrease in the Pgp level resulted in triggering of proapoptosis, while the decrease in Bcl-2 caused by bcl-2 siRNA is not sufficient to overcome the MDR of tumor due to a high Pgp level." (PMID 20470373, 2010). "MLL-rearranged tumours revealed BCL-2 hyperphosphorylation through AMPK activation, which indicates that AMPK could provide a functional role in inhibiting apoptosis in MLL-rearranged patients, and could be considered as a new potential therapeutic target." (PMID 21042412, 2010). "BCL-2 inhibitors may overcome drug resistance in human tumours that overexpress anti-apoptotic BCL-2 and BCL-XL proteins." (PMID 20515495, 2010). "Women whose tumours demonstrated the most intense BCL2 staining had the best survival." (PMID 20664598, 2010). "It promotes tumor cell survival and proliferation in vitro through up-regulation of Stat3 and Bcl2 gene expressions, the cell cycle entry from G0/1 into S-phase, and the nuclear expression of NF-κB, which contribute to the tumorigenicity of tumor cells in vivo." (PMID 20975993, 2010). "The first direct genetic connection between modulation of apoptosis and tumor growth came from the discovery that expression of the Bcl-2 gene was dysregulated via chromosomal translocation in follicular lymphoma, and that this gene is homologous to the C. elegans regulator of cell death, ced-9." (PMID 19209227, 2009). "Immunohistochemical staining revealed that in the acetylshikonin groups the expression of bax and caspase-3 increased, whereas the expression of bcl-2 decreased, suggesting that acetylshikonin induced tumor cell apoptosis through activating the pro-apoptotic bcl-2 family and caspase-3." (PMID 19594888, 2009). "Likewise, stromal intensity decreased with increased tumor grade with 100% (3/3) WD, 17% (1/6) MD, and 21% (4/19) PD displaying moderate stromal intensity for Bcl-2 staining." (PMID 19852858, 2009). "However, if BCL-2 proteins are upregulated in tumor cell this would prevent NO-dependent cell death resulting tumor progression." (PMID 19768117, 2009). "Hypoxia increases anti-apoptotic proteins (e.g., bcl-2, bcl-XL, IAP family members), arrests cell cycle (due to increased CDK inhibitors p27/Kip1 and p21/Clip1), and elevates glutathione S-transferase-π level (associated with tumor progression and invasion)." (PMID 19865518, 2009). "Interestingly, an expression profiling study of pre-treatment biopsies from 40 patients treated with AC chemotherapy identified BAG-1, BCL-2 and ER among a diverse group of 178 genes overexpressed in sensitive tumours." (PMID 19066611, 2009). "Similarly, other studies have reported an inverse relationship between epithelial Bcl-2 expression and tumor grade." (PMID 19852858, 2009).
tumor (continued). "Since resistance to apoptosis is an essential step for the tumorigenesis process, we next examined the effect of the MPA–mediated necrotic signal on different tumor cells demonstrating various mechanisms of resistance to apoptosis (Bcl2-, HSP70-, Lyn-, BCR-ABL–overexpressing cells)." (PMID 19430526, 2009). "Notably, many researchers have shown that hyperactive eIF4E in tumors mostly enhances the translation of proteins which are involved in tumor progression such as Bcl-2, survivin, cyclin D1, C-myc, and VEGF." (PMID 22649602, 2009). "Although Bcl-2 is expressed highest in malignant epithelial cells, stromal cells also express Bcl-2 but in lesser amounts, which may indicate both autocrine and paracrine effects of Bcl-2 in the tumor microenvironment." (PMID 18652667, 2008). "NFKB is activated TRADD-, TRAF3- and FADD-dependently and also plays a key role in the survival of tumor cells by inducing expression of anti-apoptotic genes such as Bcl2, Bcl2l1, vascular endothelial growth factor (VEGF), and X-linked inhibitor of apoptosis (XIAP)." (PMID 19077262, 2008). "In addition to ESR1/ERα, the top-ranked genes selected by statistical cross-analyses were MET, FOS, SNCG, IGFBP4, and BCL2, which were subsequently validated in a larger set of tumor samples (from 17 control patients and 18 TF patients)." (PMID 18928543, 2008). "In univariate logistic regression models, negative lymph nodes, poor tumour differentiation, negative ER, negative PgR and loss of bcl-2 were found to be significantly predictive of a pCR." (PMID 18380893, 2008). "One plausible explanation is that poorly differentiated tumors depend on other prosurvival pathways, and decreased Bcl-2 and Bag-1 expression is merely a marker of aggressive tumor behavior rather than mechanistically associated with aggressive biology." (PMID 18430249, 2008). "When employed in the xenograft tumorigenic model, zinc treatment of the animals results in an inhibition of tumor growth which is accompanied by an increase in the tumor cell zinc accumulation, an increase in apoptosis, and an increase in Bax level and Bax/Bcl-2 ratio." (PMID 18331646, 2008). "Telomerase activity was detected by a TRAP assay, apoptotic cells were evaluated with a Tunel assay, the expression of apoptosis-related proteins (Bcl-2 and Bax) was evaluated by immunohistochemistry and ultrastructural morphological changes in the tumor specimen were examined." (PMID 18522733, 2008). "A pCR rate below 4% was found in patients with ER-positive or PgR-positive tumours, normal bcl-2 status, low and medium proliferation activity, grade I/II differentiation, no clinical response after two cycles of chemotherapy, or positive clinical nodal status." (PMID 18380893, 2008). "However, p27 functions as a critical tumor suppressor in the context of enforced Bcl-2 expression in thymocytes." (PMID 18382684, 2008). "Bcl-2 expressed by tumour cells could sequester activated Bid, and therefore block apoptosis in the face of immune cell-derived granzyme-B." (PMID 17311012, 2007). "Both Bcl-2 and Bax expressions were increased in BP-4 group tumours." (PMID 17988381, 2007). "This variable selection procedure using an iterative stepwise discriminant analysis resulted in final models that had two predictors (tumor stage and Bcl-2 expression) when tumor stage was included in the initial list and two predictors (Bcl-2, tumor differentiation) when stage was excluded." (PMID 19455238, 2007). "The results showed that the IGFBP-4 gene therapy did not prevent the tumour establishment but it increased the tumour apoptosis which was associated with an increase in Bcl-2 and Bax expressions." (PMID 17988381, 2007). "A report from Brazil shows 45% of IHC reactivity of tumor cells for bcl-2 protein." (PMID 16759362, 2006). "All neoplasms stained variably positive for CD 34, CD 99, BCL-2 and vimentin." (PMID 16824225, 2006).